CRP (C-reactive protein)
Diseases named in the same sentence as CRP in open-access papers (continued):
Sharing a sentence is not in itself a finding about the gene and the disease.
infection (continued). "Consistent with the evidence that CRP correlates most consistently and strongly with infection severity and changes rapidly, enabling dynamic interpretation, CRP was considered likely to be the most useful biomarker in this setting for many Australian settings." (PMID 35676695, 2022). "CRP values and A/G ratios have been used as an indicator of infection and inflammation." (PMID 35631065, 2022). "In our study, 4 of 5 patients with ORN developed infections with elevated CRP levels after surgery." (PMID 36484930, 2022). "On the other hand, the actual CRP level in the serum lags approximately 60 h behind the current situation in situ, so the onset of infection in the joint might already have occurred, while the CRP value in the serum is still below the defined threshold value." (PMID 36289943, 2022). "It is well known that CRP is a sign of severe infection and systemic inflammation." (PMID 36381779, 2022). "Likewise, CRP levels have been traditionally and widely considered as indicators of infection severity." (PMID 35303001, 2022). "In addition to culture-based diagnostic methods for the detection of bacterial infections, plasmatic infection biomarkers such as C-reactive protein (CRP), procalcitonin (PCT), and interleukin (IL)-6 have long been established in clinical practice." (PMID 35883545, 2022). "In addition, ICM recommended serum D-dimer, CRP, and ESR in 2018, while European Bone and Joint Infection Society only recommended CRP in their latest guideline for identifying PJI." (PMID 35453256, 2022). "As an acute phase reactant, CRP increases significantly with somatic cell damage or infection." (PMID 35711543, 2022). "ESR and CRP are commonly used biomarkers for the diagnosis and monitoring of infection." (PMID 35926065, 2022). "Irrespective of the threshold chosen, CRP defines a group of people at particularly increased relative risk of infection death." (PMID 35535512, 2022). "When P-SEP was used in combination with IL-6 and CRP, the best negative predictive power was achieved, especially in newborns at low to medium risk of infection." (PMID 36699313, 2022). "Furthermore, CRP levels at postoperative day three, >=230 mg/L were found to be the highly sensitive cutoff value for predicting infection at day 14 and 28 post-operative days." (PMID 35991254, 2022). "Popular biomarkers of infections include C-reactive protein (CRP) and procalcitonin (PCT)." (PMID 36148158, 2022). "Patients who remained infection-free had higher mean CRP and WBC than patients who became reinfected in both the preexplantation (45.4 versus 18 mg/L and 8.6 versus 7.5 × 109/L, respectively) and prereimplantation (11.1 versus 2.8 mg/L and 6.6 versus 6.5 × 109/L, respectively) time points." (PMID 36139954, 2022). "In infections and cardiovascular diseases normal values for CRP vary between 1 and 25 mg/L." (PMID 36434581, 2022). "The diagnostic accuracy during the first fever episode of CRP, PCT and IL−6 has been largely used to predict the probability of blood stream infection prior to the results of microbial diagnosis for immunosuppressed haematological patients during the course of chemotherapy." (PMID 36431277, 2022). "Taken together, it is assumed that IL-6, similar to CRP, would comprehensively represent inflammation status caused by various causes rather than the infection itself." (PMID 36555941, 2022). "Therefore, we can use CRP and ESR combined with PCT to improve the diagnostic sensitivity for infection after IF." (PMID 35813227, 2022). "Hydromorphone dosage, age, biological sex, BMI, WBC count, and CRP have been found to be significant risk factors for developing postoperative infections in non-mechanically ventilated patients in the ICU after surgery." (PMID 35979059, 2022). "The serum CRP concentration increases during infections, especially in bacterial infections." (PMID 35307030, 2022).
infection (continued). "Our data indicated that the responses of immune pathways during infection might be minimally modulated by rOn-CRP, inconsistent with the research of human CRP." (PMID 36009776, 2022). "CRP is an acute phase protein which quickly elevates during infection or inflammation." (PMID 36035233, 2022). "Viruses, MxA levels, and MxA/CRP ratio in children with bacteremic infections." (PMID 35080443, 2022). "CRP is an early marker of inflammation and infection and is produced by the liver." (PMID 36140545, 2022). "However, in spite of higher relative risk of infection death, it is important to emphasize that the absolute rate of infection death was lower than those of cardiovascular and other death, even in people with CRP ≥10 mg/L." (PMID 35535512, 2022). "On the other hand, high CRP values in patients with CDI may be a repercussion of the presence of more serious concomitant infections of other etiology, which puts these patients at additional risk of a poor outcome of the disease." (PMID 36422354, 2022). "The mean serum levels of WBC and CRP were also higher in the infection cohort." (PMID 35303001, 2022). "Therefore, an elevated serum CRP level is an important biomarker for assessing the severity of infection." (PMID 36316726, 2022). "Here the authors show that newborn babies with signs of infection (raised C-Reactive Protein levels) have exaggerated leg reflexes and pain-related brain activity following a heel prick blood test, suggesting they may be more sensitive to pain." (PMID 35803920, 2022). "Consequently, when using CRP as an inflammation indicator, it is essential to distinguish primary inflammation from that secondary to infection." (PMID 35949598, 2022). "Moreover, the overall performance of PCT in the diagnosis of infection in ACLF patients was superior to that of CRP and comparable with presepsin." (PMID 36143057, 2022). "The three-factor model including the criteria of age, abnormal CRP, and history of recent infections might become a valuable clinical indication." (PMID 35207189, 2022). "The role of mCRP in infection is not completely understood; specifically, the reason behind the improvement in the recognition and binding ability of mCRP with ligands after the dissociation of CRP is unclear." (PMID 35874670, 2022). "In contrast to this report, we observed a negative correlation between the presence of Candida and CRP, which is indicative of fungal colonization rather than an infection caused by Candida." (PMID 36384379, 2022). "Although elevated PCT and CRP usually indicate infection, G-/G+ infection cannot be distinguished." (PMID 35432366, 2022). "The most common biochemical markers of infection/inflammation are the CRP and procalcitonin levels." (PMID 36292107, 2022). "Geniposide (the main iridoid in Gardenia) and chlorogenic acid in honeysuckle can inhibit acute and chronic inflammatory disease-related macrophage responses, reduce the release of inflammatory factors, lower C-reactive protein, and suppress infection at the same time." (PMID 35356238, 2022). "Importantly, patients with ST239 infection typically had a fever and exhibited higher levels of inflammatory markers, including C-reactive protein (CRP) and white blood cell count (WBC)." (PMID 35889965, 2022). "However, patterns 4 and 5 (patterns with fluctuating CRP values) were associated with longer antibiotic regimens, which indicates that the patients with poor CRP patterns may need longer antibiotic regimens to control infection due to unsatisfactory management responses." (PMID 35626186, 2022). "However, CRP and Lkc are acute-phase markers, typically rising at 6–12 h after infection for CRP and 5–24 h for Lkc, and then dropping when the inflammation abates." (PMID 36291945, 2022). "Knowledge of the C-reactive protein trend and deviation from the expected value may give an early indication of a possible postoperative infection." (PMID 35991254, 2022).
infection (continued). "However, studies have shown that a single low CRP measurement can underestimate the diagnosis of a serious infection, and therefore suggest relying on one or more repeated measurements." (PMID 36333682, 2022). "C-reactive protein (CRP) is considered a biomarker of infection/inflammation." (PMID 35897672, 2022). "Levels of CRP in blood begin to rise after 6–8 h of infection, and achieve to peak after 24–48 h." (PMID 35144683, 2022). "After infection, IL-6 triggers the release of CRP and peaks earlier than that of CRP." (PMID 36299571, 2022). "Higher infection level in term of a higher inflammation level and consequently higher CRP could explain more severity of disease in these patients." (PMID 36153533, 2022). "C-reactive protein (CRP) is a biomarker elevated in response to inflammation or infection." (PMID 35760050, 2022). "CRP is an inflammatory biomarker that increases in response not only to infection but also to inflammation caused by non-infectious stimuli." (PMID 35273185, 2022). "We found 513 cases of serious infections, in 29 of them a CRP value was missing." (PMID 36333682, 2022). "As it is known that DD is influenced by several factors, we included in our model age, gender, BMI, BP, pericardium thickness, effusion, PCFS, CRP, and other parameters related to the COVID-19 infection, such as the extent of the pulmonary injury and the weeks since infection." (PMID 35055360, 2022). "Thus, various novel biomarkers to determine the presence of infection have been evaluated, and some markers, such as C-reactive protein (CRP) and procalcitonin (PCT), are widely used in clinical settings." (PMID 34983420, 2022). "Infection prevalence, based on elevated CRP and AGP levels, was 36.7%." (PMID 36211493, 2022). "CRP is another commonly used marker to determine infection or inflammatory response." (PMID 35794529, 2022). "Serum C-reactive protein (CRP), D-dimer and erythrocyte sedimentation rate (ESR) are the blood biomarkers currently recommended by International Consensus Meeting (ICM) in 2018 to identify PJI, while the European Bone and Joint Infection Society recommends only CRP in their latest guidelines." (PMID 35453256, 2022). "Indeed, higher CRP levels are representative of greater infection severity, and a previous study found that higher CRP was associated with an enhanced risk of complications in DNI patients." (PMID 35453976, 2022). "Specifically, B12, ROS, T.P and Albumin could play from the very early stages of the disease an important role as biomarkers as early indicators of the infection; while, other biochemical markers, such as ferritin and CRP increase as the disease progresses." (PMID 35736249, 2022). "A slightly elevated CRP value in particular, could indicate a low-grade infection and the need for antibiotic therapy." (PMID 35303173, 2022). "Regarding the multifaceted role of CRP, the effects of CRP may differ at different infection stages." (PMID 35874670, 2022). "C-reactive protein, a nonspecific acute-phase protein produced by hepatocytes in response to IL-6 during inflammation and infection, has also been linked to HF in numerous studies and has been associated with a worse prognosis." (PMID 36014020, 2022). "Furthermore, combined treatment with dexamethasone and tocilizumab appeared to suppress CRP levels, resulting in considerably reduced efficacy in detecting secondary infections." (PMID 35566405, 2022). "Furthermore, the role of CRP as a predictor of infection, instead of inflammation, has become even more controversial since the introduction of PCT as a test in this regard." (PMID 35326841, 2022). "CRP is mainly synthesized in the liver upon interleukin- (IL-) 6 induction and its levels can increase up to 100-fold in response to several forms of tissue damage, infection and inflammation." (PMID 36741367, 2022). "Additionally, patients with elevated CRP, suggesting an active infection or inflammatory process, were excluded." (PMID 36111204, 2022).
infection (continued). "Infection or the inflammation process is accompanied by an acute phase response, a non-specific process that includes the production of acute phase proteins such as C-reactive protein (CRP), and α-1-acid glycoprotein (AGP)." (PMID 36211493, 2022). "CRP is a plasma homopentameric acute-phase inflammatory protein that is released during inflammatory processes and can increase up to 1000-fold at sites of infection or inflammation." (PMID 35681751, 2022). "Most of these are associated with inflammation generally, and thus their specificity for infection is low and could be affected by many other reasons, such as burns and malignant diseases in the case of CRP." (PMID 35615626, 2022). "CRP is synthesized primarily by hepatocytes and to a lesser extent by other cells such as smooth muscle cells and macrophages, traditionally used as markers of infection and cardiovascular events." (PMID 35514333, 2022). "Acute inflammatory marker C-reactive protein (CRP) helps to diagnose infection at an early stage." (PMID 35450383, 2022). "Furthermore, we measure pathogen-specific DNA instead of a marker for infection, like C-reactive protein." (PMID 35443013, 2022). "CRP is traditionally used as a biomarker for evaluating infection status." (PMID 35884890, 2022). "Non-microbiological analysis of the synovial fluid white cell count and polymorphonuclear (PMN) leukocytes, alpha-defensin, leukocyte esterase (LE), and C-reactive protein (CRP) were included in the new definition of PJI from the Musculoskeletal Infection Society (MSIS) guideline of 2018." (PMID 34983589, 2022). "The overall evidence suggests that PCT has much faster kinetics, both in its onset and offset, and may also be more specific than the CRP in diagnosing some infections." (PMID 35326841, 2022). "C-reactive protein (CRP) is a trace protein existing in human circulation, with a medium concentration of approximately 1 mg/L and its concentration rises rapidly under the stimulation of trauma, infection, and inflammation." (PMID 36457873, 2022). "The slightly increased and statistically relevant CRP level in our cohort could be an indication for the ongoing low-grade infection." (PMID 36212639, 2022). "However, CRP is not only just a marker of infection, but it also plays an active role in the inflammatory process." (PMID 35453906, 2022). "The increased CRP before surgery indicates that the patient may be in an inflammatory state or have an occult infection somewhere in the body." (PMID 36684164, 2022). "The degree of CRP level increase is positively correlated with the degree of infection." (PMID 35586551, 2022). "C-reactive protein is a kind of inflammatory response factor, and its expression can be significantly increased in a short time after tissue injury, usually at three days after infection." (PMID 35655728, 2022). "CRP is a systemic acute‐phase response marker for inflammation, infection, and tissue damage, which could be used as an inflammation indicator." (PMID 34874079, 2022). "When infection and inflammation occur, the level of serum CRP rises rapidly within a few hours, and reaches the peak in 24–48 h, however, serum ALB might be declined a few days after the initiation of pancreatic inflammation." (PMID 36704518, 2022). "However, due to CRP’s fast peaks and falls, it is a more sensitive marker for the course of infection than WBC." (PMID 36676644, 2022). "Our results may confirm previous findings that among laboratory parameters of infection, serum CRP value on admission correlates with its severity, and may predict the duration of hospital stay." (PMID 35628858, 2022). "Elevated CRP (30.6 mg/L) and interleukin-6 (19.33 pg/mL) levels suggested an acute-phase infection." (PMID 36211956, 2022). "If the patient had a serious infection the median CRP was 21 mg/L (IQR 6-63.5)." (PMID 36333682, 2022).
infection (continued). "Therefore, it is more common to use serum markers such as CRP and neutrophil count for infection prediction in the perioperative period." (PMID 35801326, 2022). "Moreover, in surgery, the diagnosis of infection frequently relies on infection markers (C-reactive protein, leucocytes count) and temperature, and the decision-making process is focused on prevention and prophylaxis rather than on the treatment of the IAI." (PMID 36358115, 2022). "PCT and CRP have difficulty distinguishing G- and G+ infections." (PMID 35432366, 2022). "CRP concentrations have been shown to be significantly elevated in the initial stages of infection in hospitalized COVID‐19 patients as well as at hospital discharge, but they have been observed to return to healthy levels 4 to 6 weeks following hospital discharge." (PMID 36541342, 2022). "The increase in the CRP concentration, as well as the onset concentration, would be indicative of clinical decay often followed by multi-organ injuries and massive uncontrolled inflammation that drives tissue fibrosis even months later after the infection." (PMID 36428884, 2022). "Besides CRP, the innate immune system produces acute phase response proteins, fibrinogen, and serum amyloid A, whose levels noticeably change in response to infection, tissue injury, or inflammation." (PMID 35620114, 2022). "The elevation of CRP has a positive correlation with the severity of infection." (PMID 35144683, 2022). "CRP was involved in the acute phase response and was sensitive to short-term effects such as infection, so there may be a mix of chronic and acute effects." (PMID 36685498, 2022). "CRP and neutrophil count increase during infections, but also during several other conditions." (PMID 35346147, 2022). "The normalization of CRP levels without antibiotic therapy provides strong proof for the absence of an underlying infection." (PMID 36295492, 2022). "CRP has long been used as a universal biomarker for infection-induced inflammation." (PMID 35844547, 2022). "SAA is a marker of inflammation and infection in cats, as CRP is in dogs." (PMID 36146769, 2022). "The CRP level of the male Chinese sturgeon showed a significant increase from fall to winter (p < 0.05), suggesting that it may have contracted infection or inflammation during this study period." (PMID 35514333, 2022). "In addition, Hb and CRP were found to be the main factors influencing infection in children with AL." (PMID 35463661, 2022). "For patients with CRP increasing >1.83 times, signs and indicators of infection should be strictly monitored after treatment of Tocilizumab to avoid the occurrence of fatal infection." (PMID 35799791, 2022). "CRP, WBC, and ESR are inflammation-related biomarkers, including bacteria-caused infection." (PMID 35889965, 2022). "CRP elevation was frequently seen in both infection and inflammation." (PMID 35725463, 2022). "Hs-CRP is one of the important sensitive indicators of body inflammation and infection." (PMID 36364151, 2022). "Computed tomography scores have been combined with other clinical or biological parameters, either directly related to lung function, or inflammation or infection [C-reactive protein (CRP), D-dimer, alkaline phosphatase, etc.,] with a good correlation with disease severity and death risk." (PMID 36106317, 2022). "Median CRP in patients with serious infections was 21 mg/L (IQR 6 to 63.5)." (PMID 36333682, 2022). "C-reactive protein (CRP) is a relatively accurate and sensitive marker for inflammation and infection, and could be an indication of a (possible) bacterial infection." (PMID 36536340, 2022). "CRP is a protein made by the liver and excreted into the bloodstream in response to inflammation which may protect tissues during injury or infection." (PMID 35566498, 2022). "The data collected in our study could be used to aid in the early detection of surgical infection, with the highest rise in CRP occurring on the third postoperative day in our study." (PMID 35350520, 2022).